ADIPOR1 (adiponectin receptor 1)
Diseases named in the same sentence as ADIPOR1 in open-access papers (continued):
Sharing a sentence is not in itself a finding about the gene and the disease.
tumor (continued). "In order to measure ObR, AdipoR1, adiponectin and perilipin 1 levels and localization in both tissue samples, we performed immunohistochemistry assays on adipose tissue explants from normal (hRAN) and tumor (hRAT) kidney." (PMID 31534630, 2019). "In addition, knockdown of AdipoR1, the major receptor of AdipoQ in these mouse cell lines (H7 and Panc02) followed by subcutaneous injection reduced tumor weight, size, and expression of Ki-67 (proliferation marker)." (PMID 30567565, 2018). "Moreover, AdipoR1 H-score was negatively correlated with tumor histological grade, (Kruskal Wallis ANOVA, I vs II vs III, p = 0.0080) and T-category (Mann Whitney U test, T1/2 vs T3/4, p = 0.0363)." (PMID 26931562, 2016). "Additionally, AGE, AdipoR1 and Adipo R2 expression was related to tumor grade, whereas GLO-1 and AdipoR1 to T-category." (PMID 26931562, 2016). "There is a negative correlation between AdipoR1 expression and tumor size, which suggests that the loss of AdipoR1 signaling favours tumor growth." (PMID 25360510, 2014). "Adiponectin may influence cancer risk through its well recognized effects on insulin resistance, but it is also plausible that it acts on tumor cells directly, because several tumor cell lines express AdipoR1 and AdipoR2." (PMID 20030801, 2009). "Moreover, AdipoR1 activation may reduce tumor cell migration by GSK-3β/β-catenin pathway blockage in RCC." (PMID 40227577, 2025). "We observed a decrease in AdipoR1 expression in ACHN and Caki-1 (tumor cells) incubated with hRAT-CMs compared to hRAN- and control-CMs (p < 0.001)." (PMID 31534630, 2019). "PDAC samples collected from a genetically engineered mouse (GEM), PKT (Ptf1acre/+; KrasG12D/+; Tgfbr2fl/fl), also showed a decrease of both ADIPOR1 and ADIPOR2 in tumor tissue compared to the adjacent normal acinar tissue." (PMID 29156726, 2017). "This strengthens the notion that regardless of the sex of the animal used to create adipose‐derived CM, increasing AdipoR1 protein levels increases antiproliferative effects of ADIPO, thereby suppressing tumor growth." (PMID 28676553, 2017). "While the presence of both ADIPOR1 and ADIPOR2 has previously been reported in human PDAC tumor samples, the localization and the expression level of these receptors relative to normal tissue has not been investigated." (PMID 29156726, 2017). "More specifically, when evaluating score alone AdipoR1, adiponectin, Ob-R, leptin, COX-2, F2-isoprostanes, PGF2α and α-SMA were also higher in the tissues adjacent to the tumor compared to the tumor tissues." (PMID 26431176, 2015). "To mimic the physiological and pathological states of human PTC, we established PTC tumor-bearing mouse models using PTC cell lines with NC (normal control), sh-AdipoR1 (AdipoR1 gene silencing), sh-AdipoR2 (AdipoR2 gene silencing), and sh-ULK1 (ULK1 gene silencing)." (PMID 39349421, 2024). "Nonetheless, ADIPOR1 mRNA levels were in negative correlation with gene sets related to pathways important for tumor progression, such as the TNF-α NFκB signaling pathway and MTORC, thus supporting the protective role of ADIPOR1 in CRC." (PMID 36429712, 2022). "Additionally, our case–control study’s finding of downregulated ADIPOR1 gene expression and unaltered ADIPOR2 in PBMCs was equivalent to the transcriptional trend observed in tumor-adjacent mucosa." (PMID 36429712, 2022). "The correlations between AdipoR1 or AdipoR2 and tumor TNM stage or location were not significant (p > 0.10)." (PMID 26931562, 2016). "AdipoR1 activation may also enhance the expression of different pro-angiogenic factors, such as chemokine (C-X-C motif) ligand 1 (CXCL1), MMP-2, MMP-9, and VEGF, that induce tumor blood vessel formation." (PMID 40227577, 2025). "All mice had equivalent levels of serum adiponectin and tumor AdipoR1 (data not shown)." (PMID 24594673, 2014).
tumor (continued). "Our research revealed that ADIPOR1 and ADIPOR2 are dysregulated in a wide range of tumors, and that they play critical roles in anti-tumor immunity as well as drug sensitivity, which indicated that adipose tissues might affect tumor tissues via interacting with AdipoR1/2 receptors." (PMID 36896172, 2023). "However, we cautiously hypothesize that the tumorigenic properties of ERp46 in RCC cells may not be related to an inhibitory modulation of adiponectin's tumor-suppressive signaling, as an interaction with AdipoR1 could not be established." (PMID 24594673, 2014). "However, the tumorigenic properties of ERp46 in RCC cells are not likely related to an inhibitory modulation of adiponectin's tumor-suppressive signaling, as an interaction with AdipoR1 could not be established." (PMID 24594673, 2014). "We additionally examined the differential expression of AdipoR1, AdipoR2, AGE, RAGE and GLO-I between mucinous and non-mucinous tumours." (PMID 26931562, 2016). "The proteins ADIPOR1, ADORA1 and CD46 did not demonstrate differences in expression between tumours from alive and dead patients." (PMID 20553615, 2010).
metabolic disease (9 papers, 2013 to 2025). A congenital disorder (due to inherited enzyme abnormality) or acquired (due to failure of a metabolically important organ) disorder resulting from an abnormal metabolic process. "Therefore, adiponectin, adiponectin-mimetic peptides and AdipoR1 have been implicated in various metabolic diseases and are key targets for the prevention of neurological disorders." (PMID 33849621, 2021). "Adiponectin receptors, AdipoR1 and AdipoR2 are promising targets for the prevention and treatment of metabolic diseases." (PMID 37948516, 2023). "Adiponectin activates AdipoR1 and prevents neuroinflammation and shows protective activities in various metabolic disorders." (PMID 33849621, 2021). "There are only a few studies regarding the effects of AdipoR1 on metabolic disease, therefore, we examined the therapeutic potential of AdipoR1 in this study." (PMID 29540173, 2018). "Although there are several in vivo studies describing the association of SNPs in the ADIPOR1 gene with metabolic disorders, computational analysis has not yet been undertaken on the functional and structural consequences of nsSNPs in this gene." (PMID 27294143, 2016). "Indeed, an upregulated level of Adipor1 was found in obese subjects that could be related to metabolic disorders." (PMID 38931172, 2024).
neurodegenerative disease (9 papers, 2015 to 2023). A disorder of the central nervous system characterized by gradual and progressive loss of neural tissue and neurologic function. "Other music-related genes (GMPR, SELENBP1 and ADIPOR1) associated to neuropsychiatric, neurodegenerative diseases and music performance, emerged as hub genes in consensus co-expression modules detected between AD and music estimulated transcriptomes." (PMID 36819725, 2023). "Altered gene expression in rods of AdipoR1–/– mice and its association with neurodegenerative diseases." (PMID 35015730, 2022). "Notably, and most importantly, cleaved PARP-1 was detected by stripping the PVDF membrane used for the detection of AdipoR1, so these results confirmed that AdipoR1 activation by Os-pep plays a key role in protection against neurodegenerative diseases." (PMID 33849621, 2021).
infection (8 papers, 2015 to 2025). The state of being infected such as from the introduction of a foreign agent such as serum, vaccine, antigenic substance or organism. "AMs express both AdipoRs, and their expression was modulated by A fumigatus infection, most significantly for AdipoR1, which was increased in response to infection in WT AMs but decreased in APN-deficient AMs." (PMID 40096083, 2025). "Therefore, high insulin levels associated with endotoxaemia and infection may have influenced the down-regulation of adipoR1 gene expression observed in our study." (PMID 26618091, 2015). "APN-pathway deficient AMs exhibited differential transcription of AdipoRs, and infection of APN-/- AMs decreased AdipoR1 expression." (PMID 40096083, 2025). "In tilapia infected by Aeromonas hydrophila, AdipoR1 transcription in spleen lymphocytes was upregulated at 5 days post infection (dpi)." (PMID 41249580, 2025). "Decreased AM transcription of Adipor1 and Adipor2 by infection was partially restored by AdipoRon treatment." (PMID 38979340, 2024). "AMs express both AdipoRs, and their expression was modulated by A fumigatus infection, most significantly for AdipoR1, which was increased in response to infection in WT AMs but decreased in APN−/− AMs." (PMID 38979340, 2024). "We confirmed that the ADIPOR1 expression was downregulated by half as early as 24 h post-infection, independently of the MOI used." (PMID 38257725, 2023). "We then sought to determine whether AdipoR1 signaling facilitates the ability of tilapia T cells to eliminate infection." (PMID 41249580, 2025). "This diaphonic relationship between the reprogramming of the cellular metabolism and infection could therefore be disrupted by agonists of the AdipoR1/AMPK/PPARα axis." (PMID 38257725, 2023). "In addition, for other cell organelles, peroxisome-related genes (Adipor1, Adipor2, Ppara), Cytochrome P450-related genes (Cyp2e1) and Cytochrome c-related genes (Cycs) were significantly lower in the inf + nisin group than the infection group." (PMID 38233485, 2024). "CTRP9 knockdown markedly suppressed the infection-induced upregulation of AdipoR1, CaM, CaMKKβ, and AMPK, confirming the essential role of CTRP9 in initiating the AdipoR1–Ca2+–CaMKKβ signaling cascade in response to bacterial challenge." (PMID 41249580, 2025). "The results indicate that the combination of ADIPOR1, CENPO, E2F2, and H2AC17 genes has the potential as characteristic genes for diagnosing and studying the acute phase of SFTS virus (SFTSV) infection." (PMID 37896902, 2023). "To ascertain ZIKV’s ability to inhibit the adiponectin receptor expression, we infected A549 cells with ZIKVPF13 at different MOIs and monitored the effect on both ADIPOR1 and ADIPOR2 expression after 24 h of infection." (PMID 38257725, 2023). "We demonstrated ZIKV’s ability to halve the ADIPOR1 and ADIPOR2 expression as early as 24 h post-infection." (PMID 38257725, 2023). "Noteworthy, AdipoR1 was not affected by sex, age, or weight, which was elevated in all subgroups after infection." (PMID 39840070, 2024). "With the hypothesis that AdipoR1/R2 agonists enhance OXPHOS, it is worth remembering that infection promotes aerobic glycolysis." (PMID 38257725, 2023).
adenocarcinoma (2 papers, 2016 to 2021). A common cancer characterized by the presence of malignant glandular cells. "Mucinous adenocarcinomas had marginally higher AdipoR1 and AdipoR2 expression levels (Mann–Whitney U test, p = 0.0739 and 0.0993)." (PMID 26931562, 2016).
bacterial infection (1 paper, 2025). "Administration of the AdipoR1 antibody during bacterial infection impaired the inducible expression of cytotoxic genes Perforin A and Granzyme B and pro-inflammatory cytokines IFN-γ, TNF-α, and IL-6 and reduced the ability of T cells to produce Granzyme B." (PMID 41249580, 2025). "Upon bacterial infection, AdipoR1 mediates Ca2+ influx and activates the CaM–CaMKKβ–AMPK pathway, facilitating crosstalk with TCR signaling." (PMID 41249580, 2025). "The AdipoR1 antibody was used to block AdipoR1 signaling during bacterial infection." (PMID 41249580, 2025). "Although bacterial infection induced the expansion of AdipoR1+ cells, it did not alter the T-cell composition in the AdipoR1+ or AdipoR1- cell population." (PMID 41249580, 2025). "In contrast, only a small fraction of non-T cells was AdipoR1-positive, but the frequency of this subset increased following bacterial infection." (PMID 41249580, 2025).
colon polyp (1 paper, 2008). "We generated three types of gene-deficient mice (adiponectin-deficient, adiponectin receptor 1-deficient, and adiponectin receptor 2-deficient) and investigated chemical-induced colon polyp formation and cell proliferation in colon epithelium." (PMID 18676419, 2008).
colorectal (1 paper, 2016). "AGE and AdipoR1 are possibly involved in colorectal carcinogenesis, whereas AdipoR2 and GLO-I emerged as novel independent prognostic biomarkers of adverse significance for patients with early disease stage." (PMID 26931562, 2016).
ADIPOR1 also shares sentences with these, for which no sentence is quoted: cardiovascular disease (7 papers); age-related macular degeneration (3); inflammatory bowel disease (3); acute myocardial infarction (2); Blindness (2); chronic heart failure (2); cognitive decline (2); glioblastoma (2); neurological disorders (2); ovarian cancer (2); type 2 diabetic nephropathy (2); adrenocortical carcinoma (1); alcohol dependence (1); alcoholic fatty liver disease (1); autoimmune disorders (1); Barrett esophagus (1); brain degeneration (1); brain injury (1); carcinoma in situ (1); central nervous system disorder (1); central obesity (1); Cerebral ischemia (1); chronic obstructive pulmonary disease (1); chronic renal failure (1); ciliopathy (1); Cirrhosis (1); clear cell renal cell carcinoma (1); colorectal adenocarcinoma (1); coronary atherosclerosis (1); dementia (1).
A further 46 diseases each share a sentence with ADIPOR1 in 1 paper.